NTN1 (netrin 1)
Diseases named in the same sentence as NTN1 in open-access papers (continued):
Sharing a sentence is not in itself a finding about the gene and the disease.
colorectal tumor (5 papers, 2005 to 2024). "Netrin-1 overexpression has also been cited to increase the likelihood of colorectal tumor development." (PMID 29854303, 2018). "A second question is related to netrin-1 expression in human colorectal tumours, as it would be expected that a similar selective advantage for a tumour is either to lose receptor expression (as it occurs for DCC and/or UNC5H) or to gain netrin-1 expression." (PMID 15956977, 2005). "Interestingly, brain metastases deriving from colorectal tumors showed only minor netrin-1 expression." (PMID 24647424, 2014).
endometrial cancer (5 papers, 2005 to 2025). Primary or metastatic malignant neoplasm involving the endometrium (mucous membrane that lines the endometrial cavity). "Here we describe netrin-1 upregulation in a majority of human endometrial carcinomas (ECs) and demonstrate that netrin-1 blockade, using an anti-netrin-1 antibody (NP137), is effective in reduction of tumour progression in an EC mouse model." (PMID 37532934, 2023). "In addition to the generation of a series of data, including analysis of a human cohort and preclinical experiments in mice, we have confirmed a key mechanistic role for netrin-1 in endometrial cancer resistance and progression." (PMID 37532934, 2023). "Recently, netrin-1 was found to be up-regulated during EMT, and the humanized anti-netrin-1 antibody NP137 can block metastatic progression in SCC and endometrial cancer mouse models." (PMID 38324529, 2024). "We describe netrin-1 upregulation in a majority of human endometrial carcinomas and demonstrate that netrin-1 blockade, using the anti-netrin-1 antibody NP137, is effective both in a mouse model and in patients with endometrial carcinomas." (PMID 37532934, 2023).
hepatocellular carcinoma (5 papers, 2016 to 2024). A malignant tumor that arises from hepatocytes. "The dependence receptor ligand Netrin-1 and the hepatitis C virus induce each other's expression, generating a mutual amplification loop with potential implications for the development of hepatocellular carcinoma." (PMID 27031829, 2016). "Our studies in hepatoma cells demonstrated that the generation of Neo1-ECD/TMD is facilitated by the membrane-associated Neo1-binding partner, Alk3, and that the glycosylphosphatidylinositol-anchored Hjv protects Neo1 from netrin-1–mediated degradation of Neo1." (PMID 39454953, 2024). "Netrin-1 promotes the motility of many types of tumor, such as PDAC cells, hepatocellular carcinoma cells and tumors of the nervous system." (PMID 35974411, 2022). "In human hepatocellular carcinoma (HCC), netrin-1, a laminin-related neuronal guidance molecule, negatively regulates POPDC1 expression through AKT activation." (PMID 34940515, 2021). "Hypoxia-induced Netrin-1 activation can also trigger NF-κB and p65 downstream of AKT, promoting epithelial-mesenchymal transition (EMT) in hepatocellular carcinoma (HCC) cells." (PMID 38081962, 2024).
injury (5 papers, 2018 to 2025). Damage inflicted on the body as the direct or indirect result of an external force, with or without disruption of structural continuity. "The kidney is the organ with the highest expression level of netrin-1, and the early detection of netrin-1 in urine has been observed in renal tubular ischemia-reperfusion injury." (PMID 29854781, 2018). "Therefore, serum levels of Netrin-1, NSE, and S100β are closely associated with the severity of brain injury in SAE and serve as effective predictors of short-term mortality, enhancing prognostic accuracy in clinical practice." (PMID 40714984, 2025). "Another study pointed out that serum Netrin-1 concentration decreased after brain injury and could be used as a biomarker of traumatic brain injury." (PMID 35493300, 2022). "For example, netrin-1 protected against acute lung injury sepsis in rats through decreasing the expression of IL-1, IL-6, and TNF-α, and in a porcine model of acute lung injury, through ameliorating TNF-α, IL-1β, IL-6 and IL-8." (PMID 35250531, 2021).
multiple sclerosis (5 papers, 2021 to 2023). A progressive autoimmune disorder affecting the central nervous system resulting in demyelination. "Interestingly, serum Netrin-1 levels increased in patients with neuroinflammatory multiple sclerosis or type 2 diabetes." (PMID 35246514, 2022). "Differential methylation of both NTN1 and RASA3 has been reported in blood mononuclear cells of patients affected by the neurodegenerative disease, multiple sclerosis (MS), a disease known to be influenced by high body temperature." (PMID 34122501, 2021).
Sepsis (5 papers, 2018 to 2025). Sepsis is defined as life-threatening organ dysfunction caused by a dysregulated host response to infection. "While Netrin-1 has been widely studied in cancer and angiogenesis-related disorders, and more recently in sepsis-associated acute kidney and lung injuries, its role in SAE remains underexplored." (PMID 40714984, 2025). "A study reported that the AUC of urinary netrin-1 reached 0.858 (95% CI, 0.826–0.891) in patients with sepsis-associated AKI." (PMID 29854781, 2018). "The transfection of pcDNA-netrin-1 increased netrin-1 and UNC5B expression, which resulted in a prevention of lung injury caused by sepsis." (PMID 35008701, 2021). "In a sepsis rat model, levels of netrin-1 and its receptor UNC5B were downregulated." (PMID 35008701, 2021).
subarachnoid hemorrhage (5 papers, 2019 to 2025). A serious neurological disorder characterized by intracranial hemorrhage into the subarachnoid space. "In a rat model of subarachnoid hemorrhage, administration of NTN-1 suppressed microglial activation and brain edema." (PMID 40357234, 2025). "Netrin‐1 (NTN‐1) is a novel drug to alleviate early brain injury following subarachnoid haemorrhage (SAH)." (PMID 30614619, 2019). "NTN-1 strongly exerts an anti-inflammatory properties by suppressing NF-κB pathway activation in endothelial cells and subarachnoid hemorrhage rats, and it also plays a critical role in preventing NF-κB and caspase-3/7 activation and ROS damage by microinjection in AD rats and SH-SY5Y cells." (PMID 40357234, 2025).
viral infection (5 papers, 2005 to 2025). "Although Netrin-1’s involvement in bacterial and sterile inflammation is established, its interaction with viral infections—particularly ASFV—remains unexplored." (PMID 40723441, 2025). "Our previous work implicated endothelial lipase (LIPG) as a host factor promoting HBV entry, and we subsequently discovered that Netrin-1 interacts with LIPG and recombinant Netrin-1 suppressed the viral infection." (PMID 41406170, 2025). "# O95631) and viral infection of the liver, we first measured the level of Netrin-1 mRNA (GenBank Acc." (PMID 27031829, 2016). "In this study, we establish a causative relationship between a pro-oncogenic viral infection, namely HCV, and Netrin-1, an extensively studied dependence receptor ligand, in the context of cancer development." (PMID 27031829, 2016). "While reports on Netrin signaling during viral infections are limited, a previous study demonstrated mutual amplification between Netrin-1 and hepatitis C virus via epidermal growth factor receptor pathways, indicating that Netrins can be co-opted during viral pathogenesis." (PMID 40723441, 2025). "In vivo, recombinant Netrin-1 suppressed the viral infection in humanized hepatocyte chimeric mice." (PMID 41406170, 2025). "The expression of Netrin-1 and DCC proteins was significantly lower in the Netrin-1 and DCC co-overexpression control group compared to that in the Netrin-1 and DCC co-low-expression control group, indicating successful viral infection." (PMID 40092657, 2025). "Various cell transfection or viral infection experiments have demonstrated that UNC5H or DCC, when expressed in the absence of netrin-1, can induce cell death, whereas the presence of netrin-1 is sufficient for blocking this proapoptotic activity." (PMID 15956977, 2005).
acute pancreatitis (4 papers, 2012 to 2021). An acute inflammatory process that leads to necrosis of the pancreatic parenchyma. "As macrophages are key players in acute pancreatitis, we suggest an effect of netrin-1 on macrophage dynamics and polarization." (PMID 35008701, 2021). "In the present study, we showed that netrin-1 protects against acute pancreatitis as shown by reductions in plasma amylase, MPO activity, pancreatic and pulmonary tissue damage, and pro-inflammatory cytokine production." (PMID 23029434, 2012). "In conclusion, our novel data suggest that netrin-1 is capable of improving damage of pancreas and lung, and exerting anti-inflammatory effects in mice with severe acute pancreatitis." (PMID 23029434, 2012). "However, the receptors, the signaling pathways mediating netrin-1′s beneficial effects, and the effect of netrin-1 on macrophages in acute pancreatitis are still undetermined." (PMID 35008701, 2021). "In acute pancreatitis, netrin-1 protein levels are increased within the pancreas." (PMID 35008701, 2021). "In conclusion, our present study demonstrates for the first time that netrin-1 is capable of improving pancreatic and pulmonary injury and exerting anti-inflammatory effects by inhibiting leukocyte infiltration in mice with severe acute pancreatitis." (PMID 23029434, 2012). "We first hypothesized that netrin-1 could protect against acute pancreatitis by inhibiting leukocyte infiltration and suppressing the inflammatory response." (PMID 23029434, 2012). "However, the role of netrin-1 in acute pancreatitis, to the best of our knowledge, has not been investigated to date." (PMID 23029434, 2012). "To date, the role of netrin-1 in acute pancreatitis has not been reported, however, we postulated that netrin-1 may have beneficial effects in this disease." (PMID 23029434, 2012).
brain cancer (4 papers, 2016 to 2023). A primary or metastatic malignant neoplasm affecting the brain. "Decreased netrin-1 expression has also been described in prostate and brain cancers." (PMID 27034160, 2016). "Targeting mediators such as netrin-1 and CatB could be candidates for brain cancer therapy." (PMID 30532711, 2018).
cleft lip (4 papers, 2019 to 2025). Congenital defect in the upper lip where the maxillary prominence fails to merge with the merged medial nasal prominences. "In humans, variants near NTN1 have been associated with cleft lip in human genome wide association studies." (PMID 31162046, 2019). "NTN1 variants have also been associated with cleft lip in patients, in addition to non‐syndromic heart defects, cleft palate and semicircular canal defects in mice and zebrafish models, consistent with NTN1 as a mediator of tissue fusion." (PMID 39648562, 2025). "A total of 46 cleft lip tissues from NSCL/P patients were obtained and genotyped to assess the mRNA expression of NTN1 in vivo." (PMID 31780810, 2020).
liver cancer (4 papers, 2016 to 2025). An epithelial or non-epithelial malignant neoplasm that arises from the liver. "Netrin-1-related enhancement of cell survival in a cytotoxic context has been observed in non-hepatic cancers following chemotherapy." (PMID 27031829, 2016). "In addition, NTN-1 has been described as a survival factor in a wide range of aggressive cancers including metastatic breast, pancreatic, lung, or liver cancer." (PMID 36831381, 2023). "NTN1 showed co-methylation patterns with its receptors in COAD, UCEC, PRAD, LUAD, LUSC, liver cancer (LIHC), KIRP, and KIRC." (PMID 41407823, 2025). "The effects on HCV infectivity involve the liver cancer-related epidermal growth factor receptor (EGFR), which is known to be a host receptor necessary for HCV entry and which we now show is activated by Netrin-1." (PMID 27031829, 2016).
lung fibrosis (4 papers, 2023 to 2025). "For example, macrophage-driven mechanisms, such as netrin-1–mediated adrenergic processes, have been implicated in lung fibrosis." (PMID 40655156, 2025). "NTN1 deficiency or adrenergic denervation attenuated experimentally induced lung fibrosis." (PMID 38349858, 2024). "Macrophages also play a role in the progression of pulmonary fibrosis through the secretion of netrin-1." (PMID 40723793, 2025). "It is reported that macrophage-derived netrin-1 (NTN1) drives the development of experimentally induced lung fibrosis via their axon-related functions involving adrenergic nerves remodeling, noradrenaline secretion, and α1 adrenoreceptors." (PMID 38349858, 2024). "Since netrin-1 derived from macrophages has a regulatory effect on pulmonary fibrosis, netrin-1 precisely targeting macrophages may become a new therapy with better efficacy than adrenergic antagonists in the treatment of IPF and related diseases in the future." (PMID 40723793, 2025). "Additionally, the Netrin 1 signaling pathway (Score=0.6548, FDR= 3.4698 × 10−19) has been correlated with various forms of pulmonary fibrosis, including bleomycin-induced pulmonary fibrosis." (PMID 38196613, 2023).
medulloblastoma (4 papers, 2015 to 2024). A malignant, invasive embryonal neoplasm arising from the cerebellum. "In pediatric medulloblastoma patients, netrin-1 mRNA and protein levels are elevated in medulloblastoma specimens compared with control specimens from the same patient." (PMID 30532711, 2018). "These inhibition results suggest that netrin-1 secreted by medulloblastoma cells, stimulates medulloblastoma cell invasiveness by activating the CatB via the MAPK pathway." (PMID 30532711, 2018). "Inhibition of netrin-1 by the neutralizing antibody, blocked medulloblastoma cell invasion and reduced phosphorylation of the ERK and CatB expression." (PMID 30532711, 2018). "Netrin-1 is a candidate biomarker capable of detecting the invasive, disseminated phenotype in patients with medulloblastoma and predicting their disease status." (PMID 30532711, 2018). "In patients with medulloblastoma, Netrin-1 also stimulated cell invasiveness and angiogenesis." (PMID 38375479, 2024). "We showed that netrin-1 stimulated medulloblastoma cell invasion via neogenin and UNC5B receptors." (PMID 30532711, 2018). "Urinary netrin-1 levels are also higher in medulloblastoma patients compared with controls." (PMID 30532711, 2018). "Recently, netrin-1 has been identified as a stimulator of tumor progression in breast cancer, colorectal cancer, gastric cancer, and medulloblastoma." (PMID 30532711, 2018). "Importantly, urinary netrin-1 is higher in patients with invasive medulloblastoma compared with non-invasive medulloblastoma." (PMID 30532711, 2018). "Nertin-1 (Ntn1), structurally related to the γ-chain of laminins, is the first identified member of netrin family and its overexpression has been observed in many human cancers including those of breast, pancrease, cervix, colon, medulloblastoma and rectum." (PMID 25909166, 2015). "Notably, urinary netrin-1 levels diminished after the resection of medulloblastoma in patients." (PMID 30532711, 2018).
abdominal aortic aneurysm (3 papers, 2018 to 2025). Enlargement and ballooning of the vessel that supplies arterial blood to the abdomen, pelvis and legs. "In a pioneer study, we uncovered the deleterious role of macrophage-derived Netrin-1 in promoting the development of abdominal aortic aneurysms." (PMID 31035427, 2019). "Moreover, the absence of macrophage-derived netrin-1 protected mice from developing abdominal aortic aneurysms (AAAs), suggesting that netrin-1 produced by macrophages plays a pathogenic role in the development of AAA." (PMID 40723793, 2025).
Anxiety (3 papers, 2022 to 2023). Intense feelings of nervousness, tension, or panic often arise in response to interpersonal stresses. "Loss of Ntn1 in dopamine neurons had little effect on behavior; however, we did observe an increase in anxiety-like behavior as measured by the open field assay consistent with the proposed role of dopamine in the modulation of anxiety-related behavior." (PMID 36927614, 2023). "Knocking-down hippocampal Netrin-1 in the post-weaning period by lentivirus interference alleviated visceral hypersensitivity and anxiety-like behaviors of MS rats in the later phase of life." (PMID 35966013, 2022). "Netrin-1 was identified as a key molecular cue whose long-lasting upregulation contributed to the development of visceral hypersensitivity and anxiety-like behaviors from the post-weaning period to adulthood." (PMID 35966013, 2022). "In summary, aberrant upregulation of Netrin-1 contributes to visceral hypersensitivity and anxiety-like behaviors after MS via modulating the recruitment of GluA1 in the hippocampus from the post-weaning period to adulthood." (PMID 35966013, 2022). "An elevated plus maze test was used to assess whether netrin-1 treatment induces anxiety-like behavior during the late phase of hypersensitivity (three weeks)." (PMID 35743067, 2022). "Besides, the percentage of the number of entries into open arms and the percentage of time spent in them were increased while the anxiety index was reduced significantly in EPM after the knockdown of Netrin-1." (PMID 35966013, 2022). "After knocking-down hippocampal Netrin-1 in the post-weaning period, the visceral sensitivity and anxiety-like behaviors of MS rats recovered to a great extent on PND35, a period supposed to reach the peak of visceral hypersensitivity according to the results in this work." (PMID 35966013, 2022). "Similar to mutagenesis of Ntn1 in dopamine neurons, this manipulation in GABA neurons resulted in an increase in anxiety-like behavior as demonstrated by an increased time on edge; though we only observed a trend towards a reduction in time spent in the center of the open field arena." (PMID 36927614, 2023). "Altogether, a novel hypothesis emerged that the activation of the Netrin-1/DCC/GluA1 pathway, which resulted in strengthening hippocampal LTP in MS rats, finally led to the visceral hypersensitivity and anxiety-like behaviors from the post-weaning period to adulthood." (PMID 35966013, 2022).
Arthritis (3 papers, 2019 to 2025). Inflammation of a joint. "In contrast, blockade of netrin-1 with a neutralizing antibody attenuated inflammatory bone destruction in models of arthritis and osteolysis." (PMID 40728980, 2025). "All cells used in the inflammation such as neutrophils, monocytes, macrophages, synovial fibroblasts, and bone destruction characterize this model of arthritis express the UNC-5B and netrin-1 in addition to its effects on leukocyte migration." (PMID 31663032, 2019).
breast tumors (3 papers, 2016 to 2020). "A large fraction of human breast tumors exhibits simultaneous DNA methylation‐dependent loss of expression of NTN1 and of DAPK1, a serine threonine kinase known to transduce the netrin‐1 dependence receptor pro‐apoptotic pathway." (PMID 27378792, 2016). "We show here that a substantial fraction of human breast tumors exhibits simultaneous DNA methylation‐dependent loss of expression of NTN1 and of DAPK1, a serine threonine kinase known to transduce the netrin‐1 dependence receptor pro‐apoptotic pathway." (PMID 27378792, 2016). "For example, a considerable number of human breast tumors and lung tumors show concurrent down-regulated expression of DNA methylation-dependent NTN1 and DAPK1." (PMID 32251318, 2020).
cognitive decline (3 papers, 2022 to 2024). "Netrin-1 inhibits apoptosis, inflammation, oxidation, and protects mice from memory loss and cognitive decline induced by Aβ." (PMID 38638604, 2024). "Serum Netrin-1 is reduced in AD and MCI, and patients with cognitive decline due to spinal cord injury." (PMID 38638604, 2024). "Furthermore, NTN‐1 expression in cortical and limbic regions may contribute to nonmotor symptoms such as cognitive decline and mood disturbances." (PMID 39215401, 2024).
endometrial adenocarcinoma (3 papers, 2023 to 2025). "Netrin-1 is significantly upregulated in endometrial adenocarcinoma (EC) without specific change in grades or subtypes." (PMID 37532934, 2023).